SNHG5 (small nucleolar RNA host gene 5)
Diseases named in the same sentence as SNHG5 in open-access papers (continued):
Sharing a sentence is not in itself a finding about the gene and the disease.
liver fibrosis (1 paper, 2024). "In this study, we aimed to explore the biological role of SNHG5 in liver fibrosis and its underlying mechanisms." (PMID 38438584, 2024). "Taken together, our data suggest that SNHG5 promotes liver fibrosis, at least in part, through the Hippo pathway-mediated EMT process." (PMID 38438584, 2024). "Increased SNHG5 and collagen type I alpha 1 chain (Col1A1) (liver fibrosis-related marker) were found in aHSCs compared with qHSCs." (PMID 38438584, 2024). "However, it is unclear what role SNHG5 plays in activating hepatic stellate cells (HSCs) and liver fibrosis." (PMID 38438584, 2024). "Our data suggest a fibrotic role of SNHG5 in liver fibrosis." (PMID 38438584, 2024). "All these data suggest that SNHG5 may be a promising biomarker for CHB patients with liver fibrosis." (PMID 38438584, 2024). "Our data also suggest that SNHG5 may be a potential biomarker for liver fibrosis in patients with CHB." (PMID 38438584, 2024). "We also evaluated whether liver SNHG5 could serve as a potential biomarker for liver fibrosis in CHB patients." (PMID 38438584, 2024). "To date, little is known about the biological role of SNHG5 in liver fibrosis." (PMID 38438584, 2024). "In this study, we revealed the contribution of SNHG5 in HSC activation as well as liver fibrosis." (PMID 38438584, 2024). "All these data suggest that SNHG5 may be involved in the progression of liver fibrosis." (PMID 38438584, 2024). "Obviously, SNHG5 expression was positively correlated with HAI scores as well as fibrosis stage and had a good performance in distinguishing CHB patients with liver fibrosis from healthy controls, suggesting that SNHG5 may be a promising marker for liver fibrosis in CHB patients." (PMID 38438584, 2024). "Combined with these, we demonstrate that SNHG5 has pro-fibrotic potency and that SNHG5 can regulate the Hippo pathway-mediated EMT process in liver fibrosis through binding to NF2." (PMID 38438584, 2024). "Our results suggest that SNHG5 induces Hippo-mediated EMT processes, at least in part, by interacting with NF2, and that this is an interesting mechanism for regulating liver fibrosis." (PMID 38438584, 2024).
metastatic tumors (1 paper, 2020). "Further, to identify the role of the factors in motifs with good predictive power (CDK4/SNHG5/hsa-let-7a-3p and UCA1/AKT1/hsa-miR-125b-1) in the regulation of various metastatic tumors, we used Target Mine web server and selected BH method (Benjamini-Hochberg) for P-value adjustment." (PMID 32703153, 2020).
pancreatic cancer (1 paper, 2026). "In digestive system cancers—including CRC, HCC, and pancreatic cancer—SNHG5 is generally overexpressed and promotes tumor progression." (PMID 41550840, 2026).
periodontitis (1 paper, 2023). An acute or chronic inflammatory process that affects the tissues that surround and support the teeth. "Our study reveals the specific molecular mechanism of SNHG5 in hPDLSC osteogenic differentiation, suggesting that SNHG5 could be a potential target for periodontitis therapy." (PMID 37324192, 2023). "In the present study, we attempted to expose the effect of SNHG5 on osteoblastic differentiation of PDLSCs and further probe the potential role of miR-23b in this process, in an effort to provide a new potential therapeutic target for periodontitis." (PMID 37324192, 2023). "Our study provides novel mechanistic insights into the critical role of lncRNA SNHG5 as a miR-23b-3p sponge to regulate Runx2 expression in hPDLSCs and may serve as a potential therapeutics target for periodontitis." (PMID 37324192, 2023).
polycystic kidney disease (1 paper, 2026). A usually autosomal dominant and less frequently autosomal recessive genetic disorder characterized by the presence of numerous cysts in the kidneys leading to end-stage renal failure. "Our previous studies revealed that Snhg5 is one of the most upregulated lncRNAs in multiple mouse models of polycystic kidney disease (PKD)." (PMID 41507385, 2026).
pregnancy disorder (1 paper, 2025). A disorder that is related to pregnancy. "miR-31-5p knockdown partially reverses the autophagy enhancement caused by SNHG5 silencing in trophoblast cells, suggesting a regulatory axis between SNHG5 and miR-31-5p, with potential implications in placental function and pregnancy disorders." (PMID 40565071, 2025).
pulmonary fibrosis (1 paper, 2021). Chronic progressive interstitial lung disorder characterized by the replacement of the lung tissue by connective tissue, leading to progressive dyspnea, respiratory failure, or right heart failure. "For example, SNHG5 is also involved in the p38/MAPK signal pathway, Wnt/CTNNB1, and other pulmonary fibrosis-related signaling pathways." (PMID 34349786, 2021).
thyroid cancer (1 paper, 2025). "SNHG3 and SNHG5 show relatively low expression in thyroid cancer and possess certain inhibitory effects, closely linked to their roles in autophagy regulation (the SNHG5–RBM47/USP21–FOXO3 axis) and modulation of AKT/mTOR/MAPK signaling pathways." (PMID 41234719, 2025). "In summary, SNHG5 is universally underexpressed in thyroid cancer and exerts tumor-suppressive effects through the RBM47/USP21/FOXO3 pathway and miR-510-5p-related mechanisms." (PMID 41234719, 2025). "Mechanistic studies further confirmed that miR-510-5p directly binds to and negatively regulates SNHG5, thereby affecting its functional expression in thyroid cancer cells." (PMID 41234719, 2025). "In thyroid carcinoma, certain SNHG family members (e.g., SNHG7, SNHG15, SNHG12, SNHG14) have been reported as oncogenes, while others (e.g., SNHG3, SNHG5) may function as tumor suppressors—a discrepancy warranting further investigation." (PMID 41234719, 2025).
cancer (43 papers, 2016 to 2026). A tumor composed of atypical neoplastic, often pleomorphic cells that invade other tissues. "An increasing number of studies have shown that SNHG5 is differentially expressed across various tumour cell types and is implicated in the aetiology and progression of diverse cancers." (PMID 38475928, 2024). "SNHG5 (small nucleolar RNA host gene 5) has been strongly implicated in cancer-related processes, such as cell differentiation, cell proliferation, and metastasis." (PMID 31182053, 2019). "Snhg5 is frequently described as a pathogenic lncRNA in many human diseases, including cancer." (PMID 41507385, 2026). "Nucleotide substitution of such variants might influence the expression of SNHG5 gene and is candidate genetic factor for susceptibility to cancer." (PMID 28033303, 2016). "This is because nucleotide substitutions (eg, G→T at rs6922) of the enhancer eQTLs may cause low expression of SNHG5 gene, and low expression of snoRNA U50, a product generated from introns of the SNHG5gene, can induce cancer." (PMID 28033303, 2016). "Small Nucleolar RNA Host Gene 5 (SNHG5) is located on human chromosome 6q15 and plays a significant role in the initiation and progression of various malignant tumors." (PMID 41234719, 2025). "Long noncoding RNA small nucleolar RNA host gene 5 (SNHG5) is an oncogene found in various human cancers." (PMID 38438584, 2024). "He long noncoding RNA small nucleolar host RNA 5 (SNHG5) is highly expressed in many cancers, and there is a notable correlation between the elevated expression of SNHG5 and survival outcome in cancer patients." (PMID 38475928, 2024). "Over-expression of SNHG5 contributes to the promotion of proliferation, migration and metastasis in cancer cells." (PMID 38438584, 2024). "Seven studies involving a total of 425 patients were obtained to evaluate the correlation between SNHG5 expression and cancer prognosis." (PMID 38475928, 2024). "In the EMT of cancer tissues, it was found that overexpressed SNHG5 increased the expression of epithelial-related marker E-cadherin while decreasing the expression of mesenchymal-related markers vimentin and N-cadherin, as well as transcription factors." (PMID 36711024, 2023). "SNHG5, abnormally expressed in a variety of tumors, has a close relationship with carcinogenesis, cancer progression, and patients’ prognosis." (PMID 35166647, 2022). "A query to the lnc2Cancer database showed that eight of the 14 differential hub lncRNAs (LINC00909, BZRAP1-AS1, C17orf76-AS1, HCG11, MIAT, SNHG5, SNHG15, and TP73-AS1) were associated with various types of carcinomas in previous studies." (PMID 35432537, 2022). "Scholars have reported numerous lncRNAs involved in regulating human cancer cell growth and metastasis through the modulation of the RhoA pathway, including SNHG5, LOC554202, and MALAT1." (PMID 33126743, 2020). "In summary, SNHG5 inhibits EC cancer cell development by interacting with miR-25-3p, while miR-25-3p exhibits opposite effect on EC development by targeting BTG2 mRNA." (PMID 31885582, 2019). "The abnormal expression of SNHG5 has been found in many human cancers, such as bladder cancer, gastric cancer and colorectal cancer." (PMID 31292168, 2019). "Recently, lncRNAs have gained great attention as its role in carcinogenesis and cancer progression, several known lncRNAs (SNHG5, CCAL, CASSC11) were reported to be dysregulated in CRC tissues and involved in the CRC development and progression." (PMID 30250022, 2018). "Aberrant expression of SNHG5 has been reported in several human cancers including malignant melanoma, colorectal cancer, and gastric cancer." (PMID 30166525, 2018). "This is supported by previous studies in which a variety of cancers were induced by low expression of snoRNAU50, a product generated from introns 4 and 5 of the SNHG5 gene." (PMID 28033303, 2016).
cancer (continued). "Additionally, further investigations revealed that the expression of SNHG5 was increased, while miR-20a expression was reduced in Metase-transfected cancer cells, and there is clinical evidence that miR20a promotes cancer development." (PMID 38397398, 2024). "Increasing evidence has shown the importance of SNHG5 in cancer progression and metastasis." (PMID 38438584, 2024). "Moreover, the overexpression of SNHG5 inhibited TGF-β1-induced morphological alterations in A549 cancer cells." (PMID 36711024, 2023). "Similarly, lncRNA SNHG5 has been found to promote tumorigenesis and metastasis in a variety of cancers, while other studies have indicated that it suppresses tumorigenesis." (PMID 37258567, 2023). "Therefore, additional research is needed to understand the essential functions of SNHG5 in human cancer." (PMID 36711024, 2023). "The present study aims to analyze the effect of SNHG5 on the proliferation and establish the cancer stem cell-like properties of HCC, explore the function of the SNHG5 in regulating the properties of HCC CSCs through UPF1 and Wnt-signaling pathway in vitro, and in promoting tumorigenesis in vivo." (PMID 35338348, 2022). "The roles of SNHG5 in different type of cancers have been discussed previously." (PMID 35154447, 2022). "Therefore, the role of SNHG5 in cancer remains controversial and is still a subject of ongoing research." (PMID 33176855, 2020). "Many studies have addressed the correlation between SNHG5 and cancer in various organs." (PMID 33176855, 2020). "The lncRNA SNHG5 (small nucleolar RNA host gene 5) is dysregulated in several types of cancer." (PMID 31248165, 2019). "Among the 19 TSLNRs in this study, only eight (EPB41L4A-AS2, MEG3, LINC-PINT, FTX, HCG11, HAND2-AS1, SNHG5 and TPT1-AS1) have been reported previously to be associated with malignancy, and the potential functions of the other 11 lncRNAs in human cancer remain a mystery." (PMID 30764831, 2019). "Several studies confirmed that SNHG5 played oncogenic or suppressive role in various cancers." (PMID 30166525, 2018). "However, it is important to note that SNHG5 exhibits context-dependent roles across cancer types." (PMID 41550840, 2026). "Moreover, there was an insignificant relationship between SNHG5 expression and OS in the digestive system subgroup according to cancer type (HR = 1.45, 95% CI 0.42–4.96); univariate analysis was also performed (HR = 1.31, 95% CI 0.58–2.99), and the median cutoff value was 1.79, 95% CI 0.74–4.30." (PMID 38475928, 2024). "Elevated SNHG5 expression may indicate poor prognosis in cancer patients." (PMID 38475928, 2024). "In addition, this study collected and explored only the relationship between SNHG5 and the prognosis of some cancers, which may bias the results." (PMID 38475928, 2024). "Moreover, SNHG5 can also modulate the progression of cancer by competitively binding to miRNA." (PMID 30250399, 2018). "SNHGs are a family of lncRNAs derived from snoRNAs, and SNHG1, SNHG5, and SNHG20 have been reported to participate in tumor prognosis in various cancers." (PMID 38553452, 2024). "Among the 22 SNHG families, SNHG5, SNHG7, SNHG12, and SNHG16 are all known to promote cancer progression." (PMID 37189636, 2023). "In summary, this study basically confirmed that SNHG5 promotes HCC proliferation and cancer stem cell-like properties by regulating UPF1 to activate the Wnt-signaling pathway." (PMID 35338348, 2022). "Taken together, SNHG5 plays a critical role to promote HCC cell proliferation and cancer stem cell-like properties via UPF1 and Wnt/β-catenin pathway." (PMID 35338348, 2022). "Some SE‐associated ce‐lncRNAs with high degree/betweenness were highly associated with cancer hallmarks, including lncRNAs reported in cancer (e.g., NEAT1, HOTAIR, XIST, and SNHG5)." (PMID 32460441, 2020). "Altogether, our data describe a role of SNHG5 in regulating cell survival in CRC and suggests SNHG5 as a potential candidate for RNA-based anti-cancer drug studies." (PMID 28004750, 2016).
cancer (continued). "In CRC, SNHG5 interacts with the double-stranded RNA-binding protein Staufen1 (STAU1), preventing STAU1-mediated degradation of specific mRNAs and thereby stabilizing transcripts critical for cancer cell survival." (PMID 41550840, 2026). "In summary, the current work demonstrated that the lncRNA SNHG5 might limit cell migration and invasion of LAD cancer via decreasing the EMT process, indicating that SNHG5 might be used as a target for LAD therapeutic methods." (PMID 36711024, 2023). "In conclusion, the current study revealed novel eQTLs for SNHG5 and PEX6 genes in chromosome 6.Nucleotide substitutions of the eQTLs might be candidate factors for a variety of cancers by regulating expression of the 2 genes." (PMID 28033303, 2016). "Similarly, in liver cancer, SNHG5 binds to UPF1, an RNA surveillance factor, impairing its function and resulting in the upregulation of Wnt/β-catenin pathway components, which supports stemness and self-renewal of cancer cells." (PMID 41550840, 2026). "Taken together, we speculate that there is an Lnc SNHG5/ miR-181-5p /XIAP axis in DLBC cells, and SNHG5 can serves as onco-LncRNA to regulate the development of DLBC, which in turn promote the proliferation and migration of the cancer cells." (PMID 35154447, 2022). "Because HCC is one of the deadliest cancers and has inadequate treatment options, we focused on lncRNAs that were dysregulated in HCC, LINC00862, TSPOAP-AS1, MIR17HG, and SNHG5, with their mouse counterparts being Gm19705, Mir142hg, Mir17hg, and Snhg5, respectively." (PMID 34002693, 2021). "ZFAS1 and GAS5, but not SNHG5 and SNHG8 were significantly upregulated in cancer tissues in HCC patients." (PMID 34072570, 2021).
tumor (43 papers, 2016 to 2026). "Aberrant upregulation of SNHG5 has been observed in diverse tumor types and is frequently associated with advanced disease stage and poor prognosis." (PMID 41550840, 2026). "SNHG5 is abundantly expressed across numerous tumour tissues, and elevated SNHG5 levels are significantly positively associated with poorer tumour prognosis." (PMID 38475928, 2024). "The expression of SNHG5 was downregulated in GC and linked with tumor cell proliferation and metastasis." (PMID 29156779, 2017). "In addition, increased SNHG5 has been shown to be associated with a more malignant tendency in several aspects, such as tumour burden, aggressiveness and pathological features." (PMID 33968736, 2021). "Collectively, these findings indicate that SNHG5 promotes tumor progression through diverse ceRNA-dependent pathways that are both tissue-specific and functionally heterogeneous." (PMID 41550840, 2026). "Functionally, SNHG5 promoted cell proliferation, migration, epithelial–mesenchymal transition (EMT), and suppressed apoptosis, while GNB2 overexpression partially rescued the tumor-suppressive phenotypes induced by SNHG5 silencing." (PMID 41550840, 2026). "To evaluate clinical relevance, we analyzed two independent CRC cohorts from the GEO database (GSE37182 and GSE71187), where SNHG5 was consistently overexpressed in tumor tissues relative to normal controls (p < 0.001 and p = 0.0466, respectively)." (PMID 41550840, 2026). "Through these complementary mechanisms, SNHG5 facilitates sustained activation of tumor-promoting signaling cascades, thereby enhancing proliferation, invasiveness, and resistance to apoptosis." (PMID 41550840, 2026). "These discrepancies suggest that SNHG5 is a context-dependent lncRNA, whose biological function is shaped by tumor type–specific cellular environments and signaling landscapes." (PMID 41550840, 2026). "Functional rescue assays demonstrated that GNB2 mediates SNHG5-induced tumor-promoting effects by activating the PI3K/AKT pathway, a canonical oncogenic axis." (PMID 41550840, 2026). "Knockdown of SNHG5 leads to cell cycle arrest, increased apoptosis, and reduced tumor growth in xenograft models." (PMID 41550840, 2026). "Mechanistically, SNHG5 functions primarily as a ceRNA, acting as a molecular sponge for tumor-suppressive miRNAs, thereby derepressing oncogenic transcripts and activating downstream signaling pathways." (PMID 41550840, 2026). "We found that the weight of the DLBC tumors was significantly lower in SNHG5 knockdown group in comparison with the controls (p<0.01), suggesting that knockdown of SNHG5 can inhibit the growth of the tumor in vivo." (PMID 35154447, 2022). "The results showed that downregulation of SNHG5 suppressed tumor volume and weight, therefore inhibiting the tumor growth effectively." (PMID 35338348, 2022). "We found that the expression of SNHG5 markedly increased in DLBC tumor samples compared with the normal tissue (p<0.01); moreover, we collected 90 DLBC samples and adjacent normal tissues, and the expression level of SNHG5 were compared." (PMID 35154447, 2022). "In this study, we observed the decreased expression of SNHG5 in DLBC tumor tissue and cell lines, which was consistent with the results of the bioinformatic analysis of the TCGA databased." (PMID 35154447, 2022). "SNHG5 promotes tumor cell proliferation, survival, and drug resistance by sponging miRNAs to enhance gene expression." (PMID 34026343, 2021). "In univariate analysis, advanced tumor stage/pathological stage/histological grade, metastasis, increased SNHG3/SNHG4 expression and decreased SNHG5/SNHG8 expression were potential risk factors of shorter OS." (PMID 32126023, 2020). "In hepatocellular carcinoma, SNHG5 has been shown to promote tumor cell progression by sponging miR-26a-5p and subsequently modulating the downstream target GSK3β." (PMID 31885582, 2019).